RN7SL252P (RNA, 7SL, cytoplasmic 252, pseudogene)
Gene: Miscellaneous RNA gene on chromosome 7 (96,940,068 to 96,940,364, reverse strand). Ensembl gene ENSG00000244318.
Homologues: Orthologues: chimpanzee Metazoa_SRP (97% identical), macaque Metazoa_SRP (95% identical). Paralogues in human: RN7SL1 (81% identical), RN7SL2 (81% identical), RN7SL3 (80% identical), RN7SL296P (79% identical), RN7SL743P (78% identical), RN7SL398P (78% identical), RN7SL566P (78% identical), RN7SL88P (78% identical), RN7SL126P (77% identical), RN7SL357P (77% identical), RN7SL378P (77% identical), RN7SL478P (77% identical), and 700 more.